RNU6-207P (RNA, U6 small nuclear 207, pseudogene)
Gene: Small nuclear RNA gene on chromosome X (105,676,071 to 105,676,177, reverse strand). Ensembl gene ENSG00000206864.
Homologues: Orthologues: chimpanzee U6 (99% identical), macaque U6 (97% identical), rat U6 (91% identical), guinea pig U6 (90% identical), dog U6 (89% identical), dog U6 (87% identical), dog U6 (85% identical), mouse Gm22446 (82% identical), dog U6 (79% identical), mouse Gm24735 (78% identical), guinea pig U6 (73% identical), mouse Gm26359 (72% identical), and 1 more. Paralogues in human: RNU6-128P (91% identical), RNU6-21P (91% identical), RNU6-38P (91% identical), RNU6-574P (91% identical), RNU6-1 (90% identical), RNU6-144P (90% identical), RNU6-15P (90% identical), RNU6-2 (90% identical), RNU6-20P (90% identical), RNU6-333P (90% identical), RNU6-3P (90% identical), RNU6-4P (90% identical), and 1286 more.